CSF1R (colony stimulating factor 1 receptor)
Diseases named in the same sentence as CSF1R in open-access papers (continued):
Sharing a sentence is not in itself a finding about the gene and the disease.
tumor (continued). "To conclude, exploring the molecular mechanisms modulating CSF-1R expression and function in cancer cells and whether tumor cells share the same regulatory mechanisms of immune cells will greatly help design novel approaches to target CSF-1R in cancer." (PMID 38254773, 2024). "The dysregulation of CSF-1R expression was associated with the development of an immunosuppressive TME in different cancer types, and CSF-1R favored TME interactions and the recruitment of tumor-associated macrophages (TAMs) at cancer sites." (PMID 38254773, 2024). "Tumor cells also self-secrete M-CSF, which not only attracts nearby macrophages to gather at the tumor site but also stimulates macrophages to release more M-CSF, binding to CSF-1R on the surface of tumor cells, forming a potent positive feedback mechanism." (PMID 38646440, 2024). "Understanding the receptor’s cellular localization may provide important indications for its activity and the mechanism regulating its function in tumor cells, as CSF-1R nuclear localization may suggest the transcriptional activity of the receptor." (PMID 38254773, 2024). "Similarly, CSF-1R signaling influences MDSCs to exert immunosuppressive functions, hindering anti-tumor immunity." (PMID 39457693, 2024). "For instance, interventions aimed at inhibiting M-CSF or their receptor, colony-stimulating factor 1 receptor (CSF-1R), hold the potential to modulate the tumor microenvironment, thereby impeding tumor progression and offering improved survival prospects for patients." (PMID 38646440, 2024). "In particular, CSF1R pathway inhibition could polarize myeloid cells toward exerting anti-tumor responses." (PMID 38374347, 2024). "Previous study showed that CAFs could mediate resistance to CSF-1R therapy by secreting CXCL1 and CXCL2 to recruit PMN-MDSCs, and the combined inhibition of CXCR2 and CSF-1R could overcome tumor resistance." (PMID 38291516, 2024). "The antitumor effect of CSF-1R inhibitor pexidartinib (PLX3397) is believed to be associated with reduced CD4+ T cells and elevated CD8+ T cells, resulting in markedly depletion of macrophages and inhibition of tumor growth." (PMID 39003350, 2024). "To clarify the expression of CSF-1R in the patients, we performed immunohistochemical staining of the collected tumor tissues, and two pathologists independently judged the staining intensity and positivity rate and then grouped the patients according to the scores obtained." (PMID 38303927, 2024). "By binding to CSF-1R, CSF-1 produced by tumor cells promotes TAM recruitment and polarization." (PMID 39169402, 2024). "However, the blockade of CSF-1R alone usually achieves marginal therapeutic benefits and, at most, results in delayed tumor growth." (PMID 39003350, 2024). "Currently, several CSF1R inhibitors have shown promising anti-tumor effects in clinical trials." (PMID 39416792, 2024). "In addition, CSF1 binding to CSF-1R activates the autocrine pathway of CSF-1, which endows the tumor with invasive and metastatic properties." (PMID 38303927, 2024). "More than one tumour had high/very high levels of the myeloid suppression markers CSF1R and CD68." (PMID 35866362, 2024). "However, as will be discussed later, evidence indicated that CSF-1R is an important factor in the development of tumor cell aggressiveness." (PMID 38254773, 2024). "Since the presence of CSF1R+ macrophages within tumors correlates with poor survival in various tumor types, targeting CSF1/CSF1R signaling pathway transduction that promotes tumor growth is an attractive strategy to eliminate TAMs, reduce M2 macrophage recruitment, or repolarize them." (PMID 39416792, 2024). "IL-33 or anti-CSF1R alone could control the tumor volume and tumor weight, whereas the combination of IL-33 and anti-CSF1R showed a further antitumor effect in the subcutaneous MFC-challenged 615-line mouse model." (PMID 38238529, 2024).
tumor (continued). "Therefore, when IL-34 is highly expressed with CSF-1R in tumors it marks tumor progression and lower survival." (PMID 39403370, 2024). "While blockade of the CSF1/CSF1R pathway has shown promise in reducing immunosuppressive M2-like macrophages, recent clinical trials have yielded disappointing outcomes, emphasizing the significance of treatment timing and tumor type." (PMID 38517331, 2024). "Depletion of tumor-associated macrophages by the anti-CSF1R (colony-stimulating factor 1 receptor) antibody failed to suppress murine CCA due to a compensatory infiltration of G-MDSCs with immunosuppressive features." (PMID 38397901, 2024). "Hence, these data revealed that IL-33 combined with anti-CSF1R further enhanced the antitumor effect in both abdominal dissemination and subcutaneous tumor models, indicating the importance of eliminating macrophages." (PMID 38238529, 2024). "Are CSF-1R regulation mechanisms shared between cancer cells of different tumor types?" (PMID 38254773, 2024). "Indeed, early blockade of the CSF1R-MCSF pathway combined with RT significantly inhibited tumor growth compared to phosphate-buffered saline (PBS), PLX3397 only, and RT only." (PMID 39165639, 2024). "However, detecting the CSF-1R in cancer cells is challenging due to its low expression level when compared to myeloid cells, particularly in tumor tissues dominated by CSF-1R+ monocytes/macrophages." (PMID 39457693, 2024). "One particular mechanism of therapeutic interference was revealed when paclitaxel treatment of PyMT mice was shown to increase tumor cell secretion of CSF-1 and IL-34 and addition of a CSF-1R inhibitor to the treatment regime reduced tumor growth and rates of pulmonary metastasis." (PMID 39588367, 2024). "Regorafenib is an oral multikinase receptor inhibitor that blocks tyrosine kinases active in angiogenesis (VEGFR1–3 and TIE2) and cancer growth (KIT, RET, RAF1, BRAF and BFRAFV600E), growth factors (FGFR and PDGFR), and tumor immunity promoters as the colony-stimulating factor 1 receptor (CSF1R)." (PMID 38473776, 2024). "Additionally, combining a CSF-1R signaling antagonist with paclitaxel has been shown to enhance the survival of mice with mammary tumors by slowing primary tumor growth and reducing pulmonary metastasis." (PMID 39195299, 2024). "Ongoing studies, such as this one, investigate the use of CSF‐1R inhibitor PLX3397 in the early stages of tumor development to increase the effectiveness of ICIs by boosting the number of CD8+ T cells, modifying the TME, and promoting “hot tumor” characteristics." (PMID 39631794, 2024). "Only a small macrophage cluster expressed tumor-promoting genes (Csf1r, Selenop) (Csf1r+ macs)." (PMID 38987547, 2024). "CSF-1R expression has been recently characterized in various neoplasia, where it correlates with worse prognosis, and a more immunosuppressive and aggressive tumor phenotype." (PMID 39457693, 2024). "Pexidartinib (PLX3397), a CSF1/CSF1R-signaling inhibitor, could induce a reduction in the number of TAMs and lead to a remarkable delay in tumor recurrence." (PMID 39065562, 2024). "Consistently, CSF-1– CSF-1 receptor (CSF-1R) axis blockade or macrophage recruitment blockade via C-C chemokine receptor type 2 (CCR2)-inhibition could restore immune response against tumor in cancer models." (PMID 38426089, 2024). "Moreover, a recent study revealed that blocking of CSF1R signaling inhibited AML tumor growth by disrupting paracrine signals from supporting cells." (PMID 38641704, 2024). "In addition, blocking the CSF1/CSF-1R axis can reduce the differentiation and recruitment of monocytes to tumor sites, thus further hampering the viability of existing TAMs." (PMID 39065562, 2024). "TLR agonists have been identified as potent immunostimulatory molecules capable of inducing M1 macrophage repolarization, while the CSF1/CSF1-R signaling pathway between tumor cells and macrophages is responsible for the phenotypic transition to immunosuppressive M2 phenotype." (PMID 39175095, 2024).
tumor (continued). "Also, agonistic anti-CD40 antibodies not only exert tumor suppressive effects in various cancer mouse models, but their combination with anti-CSF-1R antibodies leads to profound TAM reprogramming before their depletion." (PMID 39003350, 2024). "Moreover, we described the pro-tumoral activity of CSF-1R in tumor cells in depth and the mechanisms leading to its activation." (PMID 38254773, 2024). "Short temporal use of CSF1R antagonists in combination with T-cell-directed therapies could unleash immune-directed anti-tumor effects while preventing resistance." (PMID 39272914, 2024). "Our results indicate that regorafenib’s antagonistic effects on CSF1R might result in M1-directed polarization of monocytes, leading to enhanced anti-tumor immune response." (PMID 38374347, 2024). "Targeting CSF1-R is also a method to block the migration of MDSCs to tumor locations." (PMID 38717677, 2024). "In this co-invasion assay, selective inhibition of either HCK or PI3K p110δ are equally as effective as CSF-1R inhibition in shutting down macrophage-led tumor cell invasion while macrophages expressing constitutively active HCK promote increase tumor cell invasion." (PMID 39588367, 2024). "The dual action of surufatinib in targeting tumor angiogenesis and CSF-1R might enhance its antitumor activity, while also making it suitable for use in combination with immune checkpoint inhibitors against various types of cancers." (PMID 39055564, 2024). "In PDAC, CSF1R+F4/80+ macrophages exclusively infiltrate the tumour and enhance its growth." (PMID 38643339, 2024). "We examined the CSF1R phenotype of macrophages in the subcutaneous LLC tumor model." (PMID 36969873, 2023). "Inhibition of CSF1-R could counteract the recurrence-induced gene signature alterations in TAMs, enhance the efficacy of radiation therapy and delay tumor regrowth in pre-clinical mouse models." (PMID 37731483, 2023). "These infiltrated M-MDSCs could suppress NK cells activity, increase PD-1 expression to inhibit T cell proliferation and activate the CSF-1/CSF-1R pathway to polarize macrophages, which alter the tumor microenvironment to become pro-tumor growth." (PMID 37886177, 2023). "Interestingly, in the mouse model of brain metastases, pro-inflammatory activation of TAM which was mediated by the compensatory CSF2Rb–STAT5 signaling axis fostered tumor recurrence after CSF1R inhibition." (PMID 37731483, 2023). "First, we validated the clinical relevance of IL-10/IL-10R and CSF1R in tumor samples." (PMID 37586318, 2023). "The rationale for combining CSF1R blockade with CD40a as a strategy to overcome resistance to checkpoint inhibition was motivated by preclinical studies in which this combination fostered a proinflammatory tumor milieu, T-cell stimulation, and TAM depletion." (PMID 37964379, 2023). "Notably, the blockade of CSF1R reached comparable anti-tumor efficacy as compared to ERβ agonism in vivo." (PMID 37686465, 2023). "Similarly, discontinuation of CSF-1R blockade can lead to tumor recurrence through the accumulation of monocyte-derived macrophages." (PMID 37626849, 2023). "Notably, tumor-bearing mice treated with anti-CSF-1R showed a reduction in the colocalization of NLRP3 and ASC that resulted in a significant decrease in the formation of ASC specks." (PMID 37772994, 2023). "In a murine model, higher anti-CSF1R doses resulted in increased tumor growth and worse survival." (PMID 37964379, 2023). "Importantly, CSF1R antibody impaired the tumor growth inhibition by A20 downregulation in the mice bearing A20-silent CT26 cells." (PMID 37607946, 2023). "Tumor cells secreted CSF1/M-CSF which acted as a chemoattractant for CSF1R+ MDSCs in vitro." (PMID 37686465, 2023). "Loaded with siRNA targeting anti-CSF-1R to inhibit the survival of M2 TAMs, these nanoparticles could lead to selective depletion, tumor regression, and prolong the survival of B16 melanoma-bearing mice." (PMID 37012233, 2023).
tumor (continued). "Impairing CSF1R axis may also have a limited durable response due to infiltration of Tregs in the tumor milieu and inhibition of TRMs, which are crucial elements for a body’s immune equilibrium." (PMID 38035101, 2023). "Our results establish MTX as a macrophage reprogramming drug and evidence that its therapeutic benefits go beyond limiting tumor cell proliferation, suggesting that GSK3β might be the final target of the antitumor strategies, aiming at CSF1R or PI3Kγ." (PMID 36380627, 2023). "One of the most well-characterized techniques includes inhibiting colony-stimulating factor 1 (CSF-1) or its receptor, CSF1R, to deplete and/or decrease pro-tumor macrophages, resulting in CSF1R-dependent macrophage infiltration, thereby boosting immune-suppressing TMEs." (PMID 37426676, 2023). "In our results, when CSF1R or PLX3397 was used as monotherapy, CD8T cell, CD4T cell and Treg levels in tumor were decreased, which may be caused by the decrease of macrophage-derived chemokine." (PMID 36969873, 2023). "Nevertheless, it remains controversial whether CSF-1/CSF-1R signaling basically functions through regulating tumor immunity or tumor cell malignancy." (PMID 38067341, 2023). "The impact can be reduced by blocking the myeloid cell recruitment to the tumor; for instance, the inhibition of the CSF1/CSF1R myeloid recruitment signature expressed by both myeloid and tumor cells was shown to effectively prevent the recruitment and survival of TAMs in carcinomas." (PMID 38136307, 2023). "Hence, these findings suggest that the combination of CSF1/CSF1R signaling blockade with vaccine promoted an immune-permissive tumor microenvironment in the 4T1 tumor model." (PMID 37505292, 2023). "CSF1 is a secretory ligand of CSF1R that is secreted by tumor cells." (PMID 37092846, 2023). "Finally, the effect of CSF1R inhibitor (PLX3397) combined with ALOX5 inhibitor (Zileuton) in vivo was investigated by by xenograft tumor formation experiment in nude mice." (PMID 38124204, 2023). "Intercellular interaction analysis suggested that MFAP5 + fibroblasts could reciprocally communicate with C1QC + macrophages and other myeloid cells to remodel unfavorable conditions via MIF/CD74, IL34/CSF1R, and other tumor-promoting signaling pathways." (PMID 37344903, 2023). "Finally, we show that the CSF1R/CCR2/TGF-β Ab inhibits monocyte recruitment in patient-specific vascularized tumor models." (PMID 38076998, 2023). "To confirm whether elevated platelet-mediated tumor development depended on TAMs, we deleted TAMs in vivo using an anti-CSF1R antibody." (PMID 37064877, 2023). "Eight cases with tumor depth >10 mm showed mutations in CSF1R, ERBB4, FLT3, KDR, and NPM1, regardless of lymph node metastasis." (PMID 36780540, 2023). "Currently, there is a gap in knowledge regarding the impact of combining inhibitors of the CSF1/CSF1R signaling axis with cancer vaccines and whether this approach could enhance the anti-tumor responses in the tumor microenvironment of solid tumors." (PMID 37505292, 2023). "In a mouse model of lung cancer, BLZ945 fails to induce depletion of CSF1R+ TAMs but causes remodeling of the tumor microenvironment in which immune cells present within the tumor, such as NK or T cells, secrete large amounts of IFN-γ." (PMID 37143666, 2023). "It has already been proved that CCR2 triggers the differentiation of circulating monocytes into TAMs in the tumor microenvironment and another receptor that is required for the recruitment, differentiation, and survival of macrophages is called colony-stimulating factor-1 receptor (CSF1R)." (PMID 36109471, 2023). "Furthermore, a subset of tumor-infiltrating hematopoietic cells in young mice showed upregulated CSF1 receptor (CSF1R) expression and secreted the growth factor granulin to induce robust tumor growth and metastasis." (PMID 36945046, 2023).
tumor (continued). "Further approaches feature T cells and NK-92 cells (an immortalized natural killer cell line that can be employed for therapy) engineered with a CAR against colony-stimulating factor 1 receptor (CSF1R), a receptor expressed on both TAMs in the tumor microenvironment and M2 macrophages." (PMID 36167831, 2023). "Moreover, in the phase 1 study of diffuse-type tenosynovial giant-cell tumor (NCT01494688), anti-CSF1R antibody emactuzumab decreased tumor-infiltrating CD68/CD163+ macrophages and achieved pronounced activity (response rate: 71%)." (PMID 38008741, 2023). "By inhibiting CSF-1R, surufatinib could significantly decrease CSF-1R positive M2 TAM infiltration in tumor tissues, and increase the infiltration of M1-TAM (iNOS +) and CD8 + T cell, which result in enhancement of immune response." (PMID 35166929, 2023). "Similarly, administering a CSF-1R inhibitor during the early stages of glioma has demonstrated greater efficacy in inhibiting tumor growth and inducing adaptive immune responses." (PMID 37234776, 2023). "More importantly, the tumor growth inhibition could be attenuated by depleting macrophages with CSF1R antibody in mice bearing A20-silent tumor, suggesting that A20 regulated immune response via CRT to affect the antigen presenting process by macrophages." (PMID 37607946, 2023). "In tumours, CSF1R correlated with AXL, EPHA2 with PGFRA, and NTRK2 with PGFRB and AXL." (PMID 36890818, 2023). "The CSF-1R blockade can significantly deplete TAMs infiltration and stimulate intratumoral type I interferon signaling, which further targets the immunosuppressive TANs and elevate anti-tumor immune response during cisplatin therapy." (PMID 36845095, 2023). "Treatment with anti-CSF1R antibody alone markedly decreased metastatic tumor burden." (PMID 37872170, 2023). "First, we treated mice with a neutralizing anti-CD115 antibody, which has been shown to alter the differentiation of tumor-associated macrophages due to impaired CSF1/CSF1R signaling, without modifying monocytes in the circulation." (PMID 36104342, 2022). "Following this evidence, the rationale for combining CSF-1R blocking antibodies with PARP inhibitors led to reprogramming of the TME and significantly enhanced innate and adaptive anti-tumour immunity, which was CD8+-mediated in BRCA-deficient tumours in vivo." (PMID 36106115, 2022). "In addition, increased PD-L1 expression and decreased CSF1R level were observed in CD11c+ cells of tumor tissues from Lal–/– mice." (PMID 35917184, 2022). "Likewise, CD40 agonist, combined with CSF-1R, blockades reconditions TAMs and promotes potent anti-tumor immunity." (PMID 36303138, 2022). "As the role of TAMs in TME is appreciated to be suppressing antitumor immunity, inhibition of TAM infiltration into TME via colony-stimulating factor 1 receptor (CSF1R) blockade treatment resulted in a significant reduction of tumor growth accompanying increase of T cell infiltration." (PMID 36244976, 2022). "This, in turn negatively influences the anti-tumor effectiveness of CSF1R blockade." (PMID 36209194, 2022). "Furthermore, CSF1R inhibition enhanced antigen presentation by pleural and tumor DCs, as indicated by higher MHCII expression." (PMID 35315360, 2022). "In another, which also included the GVAX anti-tumor vaccine, the anti-CSF-1R antibody given with anti-PD-1 therapy increased the number of intratumoral PD-1+ CD8+ and PD-1+ CD4+ T cells and increased their expression of IFNγ, a cytokine known to stimulate NK cells and neutrophils." (PMID 36077755, 2022). "In addition, the suppression effect of macrophages can be abolished by inhibiting monocyte recruitment and localization to tumor tissue by targeting macrophage chemokines or their receptors (e.g., chemokine 2, chemokine 5, and CSF-1R)." (PMID 36225938, 2022).